C17orf107 (chromosome 17 open reading frame 107)
Tractability: No criterion of Open Targets' tractability assessment is met for any kind of drug.
Gene: Protein-coding gene on chromosome 17 (4,899,418 to 4,902,934, forward strand). Ensembl gene ENSG00000205710.
Subcellular location (Human Protein Atlas): Nucleoplasm
Genetic constraint (gnomAD): Loss-of-function variants: 9 observed, 8.86 expected, observed/expected ratio (o/e) 1.02, 90% interval 0.61 to 1.7. That is too few expected variants to judge how well the gene tolerates losing a copy. Missense variants: 281 observed, 251.55 expected, observed/expected ratio (o/e) 1.12, 90% interval 1.01 to 1.23. Synonymous variants: 139 observed, 120.24 expected, observed/expected ratio (o/e) 1.16, 90% interval 1.01 to 1.33.
Homologues: Orthologues: chimpanzee C17H17orf107 (98% identical), mouse 4930544D05Rik (73% identical), pig C17orf107 (72% identical), guinea pig C17orf107 (68% identical), macaque C16H17orf107 (62% identical).